PNPO (pyridoxamine 5'-phosphate oxidase)
Diseases named in the same sentence as PNPO in open-access papers (continued):
Sharing a sentence is not in itself a finding about the gene and the disease.
cancer (continued). "PNPO is an enzyme that converts pyridoxine 5′-phosphate into PLP, an active form of vitamin B6 implicated in a variety of cancers." (PMID 35127701, 2021). "Semi-quantitative analysis of the relative optical density of protein bands showed that the expression of PNPO protein was significantly high in malignant tumours than in the normal ovarian tissue and benign tumour (P < 0.05)." (PMID 29238081, 2017). "Interestingly, the specific depletion of Sgll/PNPO in RasV12DlgRNAi eye discs displayed the same effect as 4DP feeding, allowing us to exclude a major role of systemic effects of 4DP on cancer phenotypes." (PMID 38830901, 2024). "Additionally, PNPO, which converts pyridoxine 5’-phosphate into pyridoxal 5’-phosphate (PLP), an active form of vitamin B6, is implicated in several types of cancer and was aligned to GIP-9." (PMID 35629968, 2022). "Furthermore, the Gene Set Enrichment Analysis (GSEA) was applied to elucidate the biological function of PNPO in pan-cancer." (PMID 35127701, 2021). "Then, we searched for the potential relationship between PNPO mRNA expression level and clinical features, DNA mismatch repair system (MMR), microsatellite instability (MSI), tumor mutation burden (TMB), and infiltrating immune cells in pan-cancer." (PMID 35127701, 2021). "The regulation of metabolism may be the common thing with PNPO in various tumors, while participating in the regulation of different signal pathways may be the reason for its heterogeneity in pan-cancer." (PMID 35127701, 2021). "Antigen processing and presentation, and natural killer cell-mediated cytotoxicity were identified gene regulatory mechanisms of PNPO from KEGG analysis, which suggested these were the candidate signaling pathways associated with PNPO and immune system in pan-cancer." (PMID 35127701, 2021). "Furthermore, we try to analyze the correlation between the mRNA expression level of PNPO and the prognosis in human pan-cancer patients." (PMID 35127701, 2021). "PNPO might serve as a potential target for cancer treatment since they displayed abnormal expression in multiple cancers and predicted a worse prognosis in cancer patients." (PMID 35127701, 2021). "From the results, we deduced that PNPO might be positively expressed in these cancers if we enlarge the sample size." (PMID 35127701, 2021). "These suggested that PNPO may play different roles in certain cancer types, which need further to be tested in the future." (PMID 35127701, 2021). "We also searched the mRNA expression of PNPO in human pan-cancer by the TIMER database." (PMID 35127701, 2021). "GSEA was performed to explore the main biological process affected by PNPO in pan-cancer." (PMID 35127701, 2021). "The amplification of PNPO in pan-cancer may induce the abnormal expression of PLP, which leads to the dysfunction of physical metabolism in cancer development." (PMID 35127701, 2021). "In summary, our results indicated that PNPO could serve as a candidate prognostic factor among a variety of cancers." (PMID 35127701, 2021). "We performed systemic research on the roles of PNPO in human pan-cancer." (PMID 35127701, 2021). "We speculate that the mechanism of PNPO involved in human cancers could include two parts: one is involved in metabolic regulation, and the other is to function through interaction with signaling pathways." (PMID 35127701, 2021). "Pyridoxine 5′-phosphate oxidase (PNPO) is an enzyme that converts pyridoxine 5′-phosphate into pyridoxal 5′-phosphate (PLP), an active form of vitamin B6 implicated in several types of cancer." (PMID 29238081, 2017). "A well‐modulated inhibition of PNPO could therefore represent a possible anti‐cancer therapy." (PMID 38284493, 2024). "However, the research of PNPO in other kinds of cancer types is still very poor." (PMID 35127701, 2021). "The results suggested that PNPO might be involved in immune escape in human cancer immune therapy." (PMID 35127701, 2021).
cancer (continued). "These could confirm the oncogenic role of PNPO in human cancers." (PMID 35127701, 2021). "Thus, we produced the research focus on the roles of PNPO in human pan-cancer in this study." (PMID 35127701, 2021). "The data indicated that PNPO expression might influence the response of cancer patients to immune checkpoint therapy, which will contribute to further understand the mechanism of immunotherapy in treating cancers." (PMID 35127701, 2021). "Therefore, we suspected that PNPO as the key enzyme-producing PLP could also take part in immunity regulation in human cancer." (PMID 35127701, 2021). "However, the roles of PNPO in other types of cancer remain unknown." (PMID 35127701, 2021). "A significant expression difference of PNPO was found in 33 types of cancer excluding those without normal tissue data." (PMID 35127701, 2021). "Moreover, the aberrant PNPO expression was related to MMR, MSI, TMB, and tumor immune microenvironment across various types of cancer." (PMID 35127701, 2021). "Moreover, the aberrant PNPO expression was related to MMR, MSI, TMB, and drug sensitivity in various types of cancer." (PMID 35127701, 2021). "Yet, none of these studies explored the mechanisms of how PNPO is regulated in cancer." (PMID 29238081, 2017). "The function of PNPO in cancer, especially in EOC, had not been reported before." (PMID 29238081, 2017). "However, there is a lack of research on PNPO and other cancers until now." (PMID 35127701, 2021). "However, there is no related research about PNPO gene alteration in human cancers." (PMID 35127701, 2021). "Next, we found that high PNPO expression predicted poor DFI in BLCA (p = 0.034), but there was no significance in pan-cancer by Kaplan–Meier survival analysis." (PMID 35127701, 2021).
tumor (9 papers, 2015 to 2026). "We also discovered that PNPO was associated with tumor treatment response in BLCA, DLBC, KIRC, PRAD, and UCEC, especially between CR and PR groups." (PMID 35127701, 2021). "Accordingly, high expression of PDXK and PNPO, two key genes involved in PLP biosynthesis, is associated with tumor progression in some malignancies, whereas it correlates with improved outcomes in others." (PMID 41898732, 2026). "In conclusion, PNPO has a regulatory effect on lysosomal biogenesis that in turn promotes autophagic flux, leading to OC cell proliferation, and tumor formation, and is a paclitaxel-resistant factor." (PMID 38615082, 2024). "Chloroquine counteracted the promotion effect of PNPO on autophagic flux and inhibited OC cell survival, facilitating the inhibitory effect of PNPO-shRNA on tumor growth in vivo." (PMID 38615082, 2024). "We next confirmed the expression of PNPO in 33 tumor types compared to normal tissues from the online database." (PMID 35127701, 2021). "Our correlation analysis demonstrated that more than 30 immune checkpoint genes were positively correlated with PNPO expression in many tumor types, including BRCA, HNSC, LIHC, SARC, THCA, and UVM." (PMID 35127701, 2021). "To further investigate the relationship with the human immune system, we examined the relationship between PNPO expression and the tumor immune microenvironment according to the ESTIMATE algorithm and TIMER database." (PMID 35127701, 2021). "The roles of PNPO in the tumor immune microenvironment remains a research gap worth investigating in further research." (PMID 35127701, 2021). "Tumour volume from PNPO-shRNA mice was smaller than tumour volume from control SK-OV-3 (NC, control) mice." (PMID 29238081, 2017). "Silencing of PNPO induces OC cell apoptosis and decreases cell proliferation, migration and invasion in vitro and tumour formation in vivo." (PMID 29238081, 2017). "Tumour volume significantly increased in control mice compared to PNPO-shRNA mice by day 30 post-injection, persisting to the end of observation at day 40 (P < 0.05)." (PMID 29238081, 2017). "The average of tumour volume in control mice was about 150 mm3, whereas the tumour volume in PNPO-shRNA mice was less than 50 mm3 (P < 0.05)." (PMID 29238081, 2017). "WB analysis confirmed the downregulation of PNPO in the tumor tissues." (PMID 39656865, 2025). "PNPO expression was related to tumor stage in LUSC, PAAD, READ, STAD, and THCA." (PMID 35127701, 2021). "The correlations between PNPO expression and survival outcomes, clinical features, DNA mismatch repair system (MMR), microsatellite instability (MSI), tumor mutation burden (TMB), and immune-associated cell infiltration were analyzed using the TCGA, ESTIMATE algorithm, and TIMER databases." (PMID 35127701, 2021). "Additionally, PNPO protein expression was almost undetectable in PNPO-shRNA tumours compared with control tumours (P < 0.01), consistent with the low levels of immunoreactive staining of PNPO protein in PNPO-shRNA tumour sections." (PMID 29238081, 2017). "Furthermore, silencing of PNPO inhibited tumour formation in the orthotopically implanted nude mice." (PMID 29238081, 2017). "Xenografts of PNPO-shRNA-expressing cells into the nude mouse attenuated tumour growth." (PMID 29238081, 2017). "We did not detect TMPRSS2-ERG gene fusion in this patient, however, we found that TMPRSS2 gene was fused with other partners including ETV4, TRIP4, and PNPO in the visit 1 patient tumor tissue, and all these TMPRSS2 involved fusion events were rediscovered in PDXs." (PMID 26695660, 2015). "Moreover, silencing PNPO suppressed xenographic tumor formation." (PMID 38615082, 2024). "PNPO exerts its function via the regulation of MMR, MSI, TMB, tumor immune microenvironment, and drug sensitivity." (PMID 35127701, 2021). "Based on the primary tumor, lymph node, and metastasis (TNM) classification, the correlation of PNPO expression with clinical characteristics was analyzed." (PMID 30982780, 2019).
tumor (continued). "Knockdown of PNPO affects EOC cell behaviour in vitro and influences tumour formation in vivo." (PMID 29238081, 2017).
benign tumor (2 papers, 2017 to 2019). "The average concentrations of PNPO in the serum of IDC patients, the healthy controls, and patients with benign tumor were 506.37, 453.97, and 477.05 pg/ml, respectively." (PMID 30982780, 2019).
infection (2 papers, 2017 to 2019). The state of being infected such as from the introduction of a foreign agent such as serum, vaccine, antigenic substance or organism. "Silencing of PNPO after PNPO-shRNA infection was confirmed by western blot in OVCAR-3 and SK-OV-3 cells." (PMID 29238081, 2017). "The number of colonies was reduced after PNPO-shRNA infection in MCF-7 and MDA-MB-231 cells." (PMID 30982780, 2019). "Immunofluorescence microscopy showed the efficiency of lentiviruses infection with GFP and PNPO-shRNA in MCF-12A, MCF-7, and MDA-MB-231 cells and more than 90% of cells were GFP-positive." (PMID 30982780, 2019).
adenocarcinoma (1 paper, 2017). A common cancer characterized by the presence of malignant glandular cells. "Furthermore, the expression of PNPO protein was higher in EOC cell lines OVCAR-3 and SK-OV-3, but not in other two adenocarcinoma cell lines CAOV-3 and A2780 and a clear cell line ES-2, compared with non-tumorous human ovarian surface epithelial cell line HOSEpiC (P < 0.05)." (PMID 29238081, 2017).
PNPO also shares sentences with these, for which no sentence is quoted: metabolic disorders (3 papers); genetic disorder (2); hypophosphatasia (2); dependent (1); DHPR deficiency (1); Dystonia (1); early-onset epilepsy (1); epithelial malignant tumours (1); esophageal carcinoma (1); familial hyperphosphatasia (1); gastric cancer (1); GTPCH deficiency (1); homocystinuria (1); Hypoglycemia (1); hypothyroidism (1); Intellectual disability (1); kidney cancer (1); leukemia (1); liver cancer (1); lymphoma (1); neurological disorders (1); Ohtahara syndrome (1); ovarian serous cystadenocarcinoma (1); Pan (1); pancreatic adenocarcinoma (1); paraganglioma (1); Parkinson disease (1); penis squamous cell carcinoma (1); pheochromocytoma (1); prostate adenocarcinoma (1).
A further 8 diseases each share a sentence with PNPO in 1 paper.